IL18 (interleukin 18)
Diseases named in the same sentence as IL18 in open-access papers (continued):
Sharing a sentence is not in itself a finding about the gene and the disease.
Sjögren’s syndrome (11 papers, 2013 to 2025). "IL-18 has been reported to potentially cause serious damage in the lacrimal and salivary glands of Sjögren’s syndrome patients." (PMID 25962072, 2015). "This study aims to explore the contribution of the IL-37/IL-18/IL-18BP/IL-18R signaling axis to the immunopathogenesis of primary Sjögren’s syndrome, with a focus on its local and systemic expression profiles." (PMID 40430016, 2025). "The objective of this study was to explore the expression profile of the Interleukin (IL)-37/IL-18/IL-18BP/IL-18R axis in patients with primary Sjögren’s syndrome (pSS)." (PMID 40430016, 2025). "Mature IL-18 critically involved in the salivary gland inflammation and has a role in modulating the inflammatory response in primary Sjogren syndrome." (PMID 40128067, 2025). "They found that IL-18 mRNA expressions in DE associated with and without Sjogren’s syndrome were significantly higher than those of the HCs." (PMID 33531557, 2021). "Notably, Sjøgren’s Syndrome (SS) has been associated with overexpression of proinflammatory cytokines, including TNF-α, IL-7, IL-1β, IL-6, IL-10, IL-17, IL-18 and gamma-interferon (γ-IFN)." (PMID 29997338, 2018). "The IL-18/IL-37/IL-18BPa/IL-18Rα axis, via the induction of IFN-γ, appears to play a central role in the pathogenesis of Sjögren’s syndrome." (PMID 40430016, 2025). "Some of the pro-inflammatory cytokines thought to play an important role in Sjogren’s syndrome pathophysiology are the interferons (IFN), IL-12, IL-18, TNF-α, IL-1β, IL-6 and B-cell activating factor (BAFF)." (PMID 36147586, 2022). "Primary Sjögren’s syndrome patients have elevated serum levels of proinflammatory cytokines, such as IFN-γ, IL-12, IL-17 and IL-18 that are thought to contribute to the induction of exocrine gland dysfunction in pSS patients." (PMID 24551030, 2014). "In another study, the sera levels of IL-18 of 26 Italian patients with AOSD was investigated to assess the role of IL-18 cytokine as a disease marker and compared with that of 21 patients with RA, 21 patients with Sjogren’s syndrome, 20 patients with SLE and 21 healthy controls." (PMID 36032110, 2022).
airway hyperresponsiveness (10 papers, 2009 to 2025). "Studies indicate that PFAS exposure can activate inflammasomes in bronchial epithelial cells, leading to the release of pro-inflammatory cytokines (IL-1β, IL-18, and IL-33) and airway hyperresponsiveness." (PMID 41150549, 2025). "IL-18 nasally administered acted on memory type T helper 1 cells and induced airway hyperresponsiveness and inflammation, which was characterized by peribronchial infiltration with neutrophils and eosinophils." (PMID 34367377, 2021). "The nasal administration of IL-2 and IL-18 induced airway hyperresponsiveness, pulmonary eosinophilia, and goblet cell hyperplasia in wild type mice, but not in Rag2-deficient mice." (PMID 30717382, 2019). "The combination of IL-2 and IL-18 was recently found to prevent airway hyperresponsiveness and airway inflammation in a mouse model, likely through IL-12-mediated induction of IFN-γ production in NK cells." (PMID 23283012, 2009).
allergic rhinitis (10 papers, 2009 to 2025). Inflammation of the nasal mucous membranes caused by an IgE-mediated response to external allergens. "Further, in patients with allergic rhinitis, an IL-18 polymorphism is associated specifically with Alternaria allergy." (PMID 40777291, 2025). "Interestingly, clinical improvement in allergic rhinitis patients with allergen specific immunotherapy (SIT) was associated with increased IL-18 in the serum or by PBMC." (PMID 25090641, 2014). "HDM along with IL-18 was also shown to increase IL-18R in human ILC2s from allergic rhinitis patients." (PMID 40777291, 2025). "In an animal model, Levamisole (an antihelminthic) attenuated allergic rhinitis in mice with concurrent decreases in Th2 cytokines and increases in Th1 cytokines, including IL-18." (PMID 25090641, 2014). "IL-18 is up-regulated in the nasal secretions from patients with allergic rhinitis or with flour allergen change." (PMID 25090641, 2014). "Its role of IL-18 in the pathogenesis of allergic rhinitis is less clear than that of IFN-γ." (PMID 25090641, 2014). "IL-18 concentration was recently reported to be increased in the BAL fluid, but not in the nasal lavage fluid, in a mouse model of allergic rhinitis." (PMID 23283012, 2009).
intestinal infection (10 papers, 2018 to 2025). "IL-18, also known as interferon-gamma inducing factor, is primarily derived from myeloid cells but is also emerging as an epithelium-derived cytokine that contributes to the host defense against intestinal infections." (PMID 40627782, 2025). "IL-18 produced in the enteric nervous system plays a key role in intestinal homeostasis and host defense against intestinal infections." (PMID 37513690, 2023). "IL-18 is emerging as an IL-22-induced and epithelium-derived cytokine which contributes to host defence against intestinal infection and inflammation." (PMID 35169117, 2022). "More IL-18 is produced downstream of the activated inflammasome to exert its biological functions when gastrointestinal infection and intestinal inflammation occur." (PMID 36497018, 2022). "Caspase-11 is the murine ortholog of human caspase-4, which was reported to mediate IL-18 secretion and enterocyte pyroptosis during intestinal infection." (PMID 30138458, 2018). "In addition, both IL-22 and IL-12 also induce IL-18 expression in epithelial cells during intestinal infection." (PMID 31707260, 2019). "How exactly IEL are rapidly activated to deploy Gzms in the presence of intestinal infection is unknown, but may depend on their sensing epithelial danger signals such as IL-18,49 ligands for activating receptors or even metabolic changes in the infected epithelial cell." (PMID 39137883, 2024). "In general, intestinal epithelial cells without intestinal infection and inflammation under physiological conditions are the main source of IL-18; IL-18 released by intestinal epithelial cells has the function of promoting intestinal epithelial repair, renewal, and maturation." (PMID 36497018, 2022). "However, elevated IL-18 levels in NLRC4V341A-expressing mice did not induce intestinal pathology and did not impact on gastrointestinal infections with NLRC4-activating pathogens." (PMID 38090573, 2023).
juvenile idiopathic arthritis (10 papers, 2006 to 2024). Juvenile idiopathic arthritis (JIA) is the term used to describe a group of inflammatory articular disorders of unknown cause that begin before the age of 16 and last over 6 weeks. "IL-18 might also be elevated in systemic juvenile arthritis, thus the IL-18 level could help to differentiate autoinflammatory diseases or primary MAS (HLH) from other diseases, such as FPIES or other allergic or infectious severe diseases." (PMID 34640385, 2021). "Because high serum IL-18 induction has also been observed in the systemic type of juvenile idiopathic arthritis (JIA), we investigated whether similar genetic skewing is present in this disease." (PMID 16563174, 2006). "Notably, the reduction effect of canakinumab on the concentrations of IL-1RA, IL-6, IL-18 and S100A12 in our cohort had been confirmed recently in a systemic juvenile idiopathic arthritis cohort." (PMID 34640417, 2021).
renal cell carcinoma (10 papers, 2013 to 2025). "In this study, we evaluated the contribution of IL-18 genotypes to renal cell carcinoma (RCC) in Taiwan via the genotyping of IL-18 -656 (A/C), -607 (A/C), and -137 (G/C)." (PMID 30925760, 2019). "The NLRP3 inflammasome, along with IL-18 and IL-1β, plays a significant role in promoting the development of bladder cancer (BC) and renal cell carcinoma (RCC)." (PMID 40718836, 2025). "However, it remains unknown the effect of IL18 promoter methylation on the occurrence, development and immune infiltration of tumors, especially renal cell carcinoma." (PMID 36707882, 2023).
Rotavirus infection (10 papers, 2015 to 2025). Infection with any of the rotaviruses. "Next, we investigated the kinetics of IFN-λ3 and IL-18 production in primary IECs from mouse intestine organoids of both Trim29+/+ and Trim29−/− mice at 10 h, 20 h, and 30 h after Rotavirus infection." (PMID 39396665, 2025). "The Trim29−/− suckling mice exhibited over 3-fold increase in IFN-λ3 and IL-18 production compared to their wild-type Trim29+/+ counterparts following rotavirus infection." (PMID 39396665, 2025). "We found that knockout of TRIM29 led to the peak production of IFN-λ3 and IL-18 at 20 h post-infection, with a subsequent decrease at 30 h after Rotavirus infection." (PMID 39396665, 2025). "IL-22 release induced a state of gene expression in intestinal epithelial cells that was protective against rotavirus infection, while IL-18 aided in the elimination of rotavirus-infected cells." (PMID 36298668, 2022). "Additionally, Trim29IEC-KO suckling mice produced over 3-fold more IFN-λ3 and IL-18 than did wild-type Trim29fl/fl littermates, in intestines with rotavirus infection." (PMID 39396665, 2025). "Combination therapy with IL-18 and IL-22 may be a treatment for rotavirus infection since IL-22 and IL-18 can induce expression of one another." (PMID 37006293, 2023). "NLRC4 activation during rotavirus infection leads to the release of IL-18 and IL-22." (PMID 36298668, 2022). "Nlrp9b−/− mice, and mice selectively deficient in caspase-1 in epithelial cells, but not Il18−/− mice, were highly susceptible to rotavirus infection, in terms of exaggerated diarrhea." (PMID 30717382, 2019). "As a critical mechanism of host defense, GSDMD activation–mediated IL-18 release contributes to the killing and clearance of gastrointestinal pathogens in intestinal cells and immune cells, which drives anti-rotavirus immunity and protects mice against rotavirus infection." (PMID 39927458, 2025). "Of interest, several IFN inducible genes (OAS1, MX1, IL18, IITP3, TAP1, and RSAD2) as well as several cytokines and chemokines (CCL5, CXCL10, CXCL11, IL8, and CCL15) were upregulated by rotavirus infection." (PMID 28210256, 2017). "Rotavirus infection was prevented and cured via the signaling pathway mediated by TLR5 and NOD-like receptor C4 (NLRC4), which led to production of IL-22 and IL-18 (mimicking the Th17-polarization)." (PMID 26213635, 2015). "Furthermore, DHX9 pairs with Nlrp9b to sense short dsRNA, forming inflammasome complexes that promote the maturation of interleukin-18 and GSDMD-induced pyroptosis, thus providing resistance against rotavirus infection in IECs18." (PMID 38594251, 2024). "However, IFN-λ3 and IL-18 were barely expressed in intestines from both wild-type Trim29fl/fl and Trim29IEC-KO suckling mice without rotavirus infection." (PMID 39396665, 2025). "Additionally, although NLRP6 and NLRP9b were barely expressed in human HT-29 IECs, NLRP6 and NLRP9b were induced in HT-29 IECs after EMCV and rotavirus infection, respectively, suggesting thatNLRP6 and NLRP9b control the upregulation of IFN-λ3 and IL-18 upon knock down of TRIM29." (PMID 39396665, 2025). "It is widely believed that interleukin-22 (IL-22) inhibits rotavirus infection by activating the STAT3 signaling pathway and upregulates the expression of antimicrobial genes in the gut, including antimicrobial peptide β-defensin (BD-2), cytokine IL-18, and interferon- λ (IFN-λ)." (PMID 37006293, 2023).
acute GVHD (9 papers, 2006 to 2025). "Acute GVHD is associated with the secretion of IL-12 and IL-18, which are known to promote NK cell functional maturation." (PMID 31649665, 2019). "On the contrary, administration of IL-18 can effectively prevent the occurrence of chronic GVHD without causing the immune deficiency and mortality associated with acute GVHD." (PMID 40943537, 2025). "We demonstrated, by an immunohistochemical analysis, that enhanced IL-18 expression was found in chronic GVHD (sclerodermoid type) as well as acute GVHD (grade I)." (PMID 26690141, 2015). "IL-18 is expressed in humans as well as in animal models with acute GVHD." (PMID 26690141, 2015). "The serum levels of IL-18 correlate with the severity of acute GVHD." (PMID 26690141, 2015). "In the mouse, IL-18 has a protective effect on CD4(+)-mediated acute GVHD, and blockade of IL-18 accelerates acute GVHD-related mortality in mice." (PMID 18818761, 2008). "Previous experiments have demonstrated that cytokines such as IL-12 and IL-18 induce donor anti-host CTLs in chronic GVHD mice and can ameliorate chronic GVHD, or even stimulate the development of acute GVHD." (PMID 16859527, 2006). "While IL-18 has been shown to induce IFN-γ production and CTL activity under specific conditions both in vitro and in vivo, neutralization of IL-18 did not inhibit IFN-γ production or CTL activity in an experimental model of acute GVHD." (PMID 40943537, 2025). "However, regardless of treatment schedule (treatment on days 0 to 5 or days 8 to 13 after induction of chronic GVHD), IL-18 treatment generated anti-host CTLs, but did not induce acute GVHD." (PMID 16859527, 2006). "This suggests that IL-18 may not be essential for T cell activation during acute GVHD." (PMID 40943537, 2025).
autoinflammatory syndrome (9 papers, 2015 to 2024). A group of disorders of the innate immune system characterized by attacks of seemingly unprovoked inflammation without significant levels of either autoantibodies or autoreactive T cells more characteristic of autoimmune disease. "IL-1β, IL-18, and IL-33 were within normal limits or undetectable, and no mutations were found in genes related to the pathogenesis of autoinflammatory syndromes (MEFV, MVK, TNFRSF1A, NLRP3, and NLRP12)." (PMID 34829952, 2021). "Interestingly, patients suffering from NLRP1-associated autoinflammatory syndrome (also characterized by high IL-18 and IL-1β levels) had higher peripheral blood transitional B cells, bearing the regulatory phenotype CD24highCD38highCD27low/neg." (PMID 38392193, 2024). "For example, autoinflammatory syndromes with gain-of-function mutations in NLRP3 are mainly driven by myeloid-production of IL-1β, while syndromes due to gain-of-function mutations in NLRC4 are associated with epithelial-production of IL-18." (PMID 39468985, 2024). "Additionally, the inappropriate release of IL-1β and IL-18 has been demonstrated to elicit urticaria in autoinflammatory syndromes." (PMID 38539560, 2024).
bladder cancer (9 papers, 2013 to 2024). "The findings demonstrate a substantial decrease in the population of IL-18/-21-pretreated eNK cells, with fewer than 1 × 104 cells persisting in association with bladder cancer cells after the washing procedure." (PMID 38548803, 2024). "Our findings demonstrate that the combination of RP116 reovirus and IL-18/-21-pretreated eNK cells exhibited promising additive anti-tumor effects against different grades of bladder cancer cell lines (5637, HT-1376, and 253J-BV)." (PMID 38548803, 2024). "In our study, the analysis of genes PRKCZ, PTK2, and IL-18 underscores their significant roles in bladder cancer carcinogenesis, progression, and survival outcomes." (PMID 39064604, 2024). "The results showed a significant reduction in the number of IL-18/-21-pretreated eNK cells that remained among the bladder cancer cells after washing." (PMID 38548803, 2024). "One interesting finding is the overall upregulation of IL18 in tumors since it was previously shown that serum levels of IL18 were higher in bladder cancer patients than in healthy controls." (PMID 31779626, 2019). "However, for all bladder cancer cell lines, the number of surviving cancer cells decreased based on the number of IL-18/-21-pretreated eNK cells." (PMID 38548803, 2024). "Cytokines released in patients with bladder cancer treated with BCG include TRAIL (TNF-related apoptosis-inducing ligand), IL-2, IL-8, IL-18, IL-12, IFN-γ, and TNFα." (PMID 36119107, 2022).
cerebral infarction (9 papers, 2016 to 2025). An ischemic condition of the brain, producing a persistent focal neurological deficit in the area of distribution of the cerebral arteries. "In conclusions, our results suggested that polymorphisms of IL-1α −899C/T, IL-6 −572C/G and IL-18 −607C/A were positive correlated with increased the risk of cerebral infarction." (PMID 27679860, 2016). "For IL-18 −607C/A polymorphism, 6 articles contained 1793 cerebral infarction patients and 1661 healthy controls." (PMID 27679860, 2016). "Our result found that the frequency of A allele was a little higher in controls than that in patients (55.0% versus 48.1%), but the A allele of IL-18 −607C/A polymorphism was associated with increased the risk of cerebral infarction (A versus C: OR=0.76, 95% CI=0.69–0.84, P<0.00001)." (PMID 27679860, 2016). "Our result showed that IL-1α −899C/T and IL-18 −607C/A (under all the genetic models), and IL-6 −572C/G (under the allelic model, heterogeneity model and dominant model) were associated with increased the risk of cerebral infarction (P<0.05)." (PMID 27679860, 2016). "In conclusion, IL-1α −899C/T, IL-6 −572C/G and IL-18 −607C/A might be risk factors for cerebral infarction development." (PMID 27679860, 2016). "Our results found that polymorphisms of IL-1α −899C/T and IL-18 −607C/A (under all the genetic models), and IL-6 −572C/G (under the allelic model, heterogeneity model and dominant model) were associated with increased the risk of cerebral infarction." (PMID 27679860, 2016). "In summary, our study showed HAX-1 attenuated microglial pyroptosis both in vivo and in vitro and reduced the inflammatory responses in cerebral infarction through inhibition of proinflammatory cytokines such as IL-1 and IL-18." (PMID 38811533, 2024). "The results revealed that expressions of the IL-1β and IL-18 proteins increased in the cerebral infarction cortex of MCAO rats." (PMID 33820869, 2021). "SFN treatment of rats with middle cerebral artery occlusion inhibited the activation of inflammatory vesicles and the expressions of caspase-1, IL-1β and IL-18, reduced the volume of cerebral infarction, improved the score of neurological function, and reduced neutrophil infiltration." (PMID 34526897, 2021). "Both NADPH and Apocynin inhibit the expression of NLRP3, ASC, caspase-1, IL-1β, and IL-18 in the ischemic cerebral cortex in a rat cerebral infarction model, and reduce the volume of cerebral infarction, improve survival after infarction, and restore neurological function." (PMID 34526897, 2021). "The present study showed that Sino significantly decreased the mRNA levels of pro-inflammatory cytokines, including IL-1β, IL-6, IL-18, and TNF-α, in the tissues surrounding the cerebral infarction." (PMID 27724964, 2016). "Calycosin significantly reduced neurological impairments and brain infarction in a dose-dependent manner, alleviated neuronal damage and decreased the expression of pyroptosis-related markers, including NLRP3, GSDMD, HMGB1, IL-1β, IL-18, and caspase-1." (PMID 40606597, 2025). "Compared with the model group, AST-IV significantly reduced the neurological function deficit score, cerebral infarct volume, and the protein levels of NLRP3, Caspase-1, pro-IL-1β, IL-1β, pro-IL-18, and IL-18 in brain tissue, and inhibited the expression of phosphorylated NF-κB protein." (PMID 38601463, 2024).